INS (insulin)
Diseases named in the same sentence as INS in open-access papers (continued):
Sharing a sentence is not in itself a finding about the gene and the disease.
Hyperglycemia (continued). "This is evident from the fact that within days of delivery of the placenta, there is a substantial increase in maternal insulin sensitivity and the hyperglycemia of GDM generally resolves." (PMID 37650554, 2023). "The improvement in insulin action lowers blood glucose levels, which prevents glucotoxicity, the harmful effects of hyperglycemia on β-cells." (PMID 37241737, 2023). "Particularly, women with fasting hyperglycaemia or early‐onset GDM are more insulin resistant, and they often need anti‐diabetic medication." (PMID 36484476, 2023). "Impaired GLUT4 expression and translocation in insulin-sensitive tissue contributes to the hyperglycemia observed in T2DM." (PMID 37639557, 2023). "Hyperglycemia can also significantly trigger insulin secretion, and hyperinsulinemia can overactivate insulin signaling." (PMID 38020199, 2023). "From the present observations, STZ-induced hyperglycemia is characterized by a high level of low serum insulin level, high glucose level, and high HbA1C level with an elevation of calculated HOMA-IR." (PMID 36825257, 2023). "In HFD-induced diabetic rats, the intraperitoneal administration of RA (200 mg/kg/day for 28 days) dose-dependently ameliorated hyperglycemia and increased insulin sensitivity assessed by the oral glucose tolerance test (OGTT)." (PMID 36982168, 2023). "Insulin as first-line therapy has been recommended if the glycated hemoglobulin level ≥7.5%-9.0% and symptomatic hyperglycemia are noted." (PMID 36650625, 2023). "Impaired insulin release and IR can also impair peripheral glucose uptake and hepatic gluconeogenesis, resulting in hyperglycemia." (PMID 37397470, 2023). "The glycemia-lowering action of low-dose ABA in vivo reduces stimulation by hyperglycemia on β-cells and consequently insulin release." (PMID 36674711, 2023). "Despite an ∼ 2-fold increase in active GLP1, olanzapine-induced hyperglycemia, and reductions in serum insulin were unchanged by sitagliptin, while glucagon was elevated in animals that received both drugs." (PMID 36937886, 2023). "In subjects with T2DM, the restoration of the first phase of insulin secretion after a mixed meal improved postprandial hyperglycemia and suppressed endogenous lipolysis, resulting in the decrease of plasma NEFA levels." (PMID 37242267, 2023). "Threshold values and the duration of hyperglycemia, when insulin treatment is recommended in extremely premature infants, differ from threshold values in infants and infants later in life." (PMID 37892314, 2023). "HbA1c is a crucial clinical indicator for determining long-term hyperglycemia, as insulin resistance typically leads to increased HbA1c and insulin content." (PMID 38275632, 2023). "Ins1-/-:Ins2f/f mouse β cells lose about 50% of insulin production, resulting in robust hyperglycemia, β cell proliferation, hormone expression disorders and alleviation of ER stress." (PMID 37244925, 2023). "For hyperglycemia, insulin was delivered by subcutaneous injections or BCD button clicks, respectively: Inj‐Insulin (n = 4) and BCD‐Insulin (n = 4)." (PMID 36684080, 2023). "It should be noted that PPARγ has received a substantial attention owing to its effect on reducing hyperglycemia by increasing insulin sensitivity and decreasing hepatic glucose production." (PMID 37710214, 2023). "Patients with GDM lack sufficient insulin production to combat the aggravation of insulin resistance, which leads to hyperglycemia." (PMID 37680884, 2023). "Comparative assessment of measures of glucose homeostasis and insulin resistance in relation to the circulating lipids at preconception with a large sample size provided an integrated view of the effects of hyperglycaemia on systemic metabolism." (PMID 36782297, 2023). "It is characterized by the elevation of blood sugar levels, termed hyperglycemia, resulting from dysregulations in insulin secretion and/or function." (PMID 38146555, 2023).
Hyperglycemia (continued). "In insulin-sensitive individuals, hyperglycemia stimulates insulin release from pancreatic β-cells and inhibits gluconeogenesis in the liver." (PMID 36979669, 2023). "This panel recommended using insulin-based therapy (IBT) in T2D patients with symptoms of hyperglycemia." (PMID 37468901, 2023). "T2DM is responsible for a 5% increase in premature mortality due to its complications, which start with hyperglycemia and proceed to a combination of resistance to insulin action, insufficient insulin secretion, and excessive glucagon breakdown and secretion." (PMID 36986806, 2023). "Hyperglycemia induces oxidative stress both directly and indirectly in BC cells in part by increasing levels of insulin/IGF-1 as well as inflammatory cytokines." (PMID 36849958, 2023). "Rodents with SCN dysfunction display global or partial circadian gene disruption and easily developed IGT, hyperglycemia, hyperinsulinemia, decreased insulin secretion and sensitivity, and β-cell defects in the pancreas." (PMID 38089624, 2023). "Deteroirtion of the insulin production in islet β cells or dysfunction of the regulation between glucose transporter translocation in cell membrane, or both, lead to hyperglycemia." (PMID 37507664, 2023). "The use of antihyperglycemic agents instead of insulin is the preferred treatment method for patients with mild hyperglycemia after transplantation." (PMID 36831005, 2023). "Metformin acts as an insulin sensitizer, which together with lifestyle changes, improves glucose uptake of patients, and thereby reduces hyperglycemia." (PMID 36980281, 2023). "Impaired insulin sensitivity was also observed in offspring exposed to hyperglycemia in utero due to maternal GDM or type 1 diabetes compared with offspring from the background population." (PMID 37414142, 2023). "The magnitude of hyperglycemia and reduced insulin secretion gradually increased over 4 months, thereby defining more accurately and extensively the course of the diabetic phenotype in this genetically inbred animal strain." (PMID 36674879, 2023). "The glutathione antioxidant system is dysregulated or imbalanced due to increased ROS production induced by hyperglycemia that leads to insulin resistance and pancreatic β-cell death." (PMID 37755075, 2023). "Fasting glucose elevation is characterized by increased hepatic glucose production and decreased early insulin secretion, whereas postprandial hyperglycemia is mainly due to peripheral IR." (PMID 37886939, 2023). "We should pay more attention to the adverse effects of perinatal hyperglycemia and continue to give appropriate insulin treatment even if patients have passed the acute phase of hypertriglyceridemia-induced acute pancreatitis." (PMID 37920254, 2023). "Three (4%) subjects in the placebo group encountered hyperglycemia requiring rescue insulin therapy, and one (1%) subject in the TENS group had hyperglycemia being rescued by add-on OAD." (PMID 36792682, 2023). "Hormone release was proportional to the quantity of glucose present, and the complex was designed to sequester insulin in the subcutaneous space during normoglycaemia and release the hormone during hyperglycaemia via competition with ambient glucose molecules." (PMID 37685946, 2023). "Palmitic acid has antibacterial activity, and a compressed mixture of insulin and palmitic acid can sustain a reduction in hyperglycemia in rodents." (PMID 36777625, 2023). "This proposes that even a mild infection with severe acute respiratory syndrome coronavirus 2 (SARS-CoV-2) infection can trigger a systemic response that can lead to downstream manifestations including insulin resistance and severe hyperglycemia." (PMID 37456416, 2023). "The trial showed that the SB fruit and the oil-free fruit significantly suppressed the postprandial peak insulin response, and stabilized postprandial hyperglycemia and subsequent hypoglycemia." (PMID 35971438, 2023).
Hyperglycemia (continued). "An insulin pellet was inserted when fasting blood glucose exceeded 450 mg/dL to minimize the detrimental effects of overt hyperglycemia." (PMID 36868230, 2023). "Chronic hyperglycemia can lead to the dysfunction of pancreatic β-cells, thus lowering insulin secretion." (PMID 37242267, 2023). "When energy consumption is not adequate for energy expenditure and when the pancreatic response is not sufficient to overcome rising carbohydrate levels and progressing insulin insensitivity, this results in a state of hyperglycaemia." (PMID 37627482, 2023). "Using both a rodent dietary and genetic model of hyperglycemia and β-cell dysfunction, we show that proinsulin trafficking is impeded at the Golgi and coincides with the decreased appearance of nascent insulin granules at the plasma membrane." (PMID 36997560, 2023). "Although the number of women was small, those with the most severe hyperglycemia (both fasting and postload) had evidence of the most severe defects in insulin secretion and sensitivity." (PMID 36950879, 2023). "Among the SIRT family, SIRT1 is located in the nucleus, and ameliorates hyperglycemia by promoting insulin secretion and β cell expansion." (PMID 37601108, 2023). "The actions of naringenin include improving hyperglycemia, insulinemia, insulin sensitivity, pancreatic cell performance, and lipid profile." (PMID 37894687, 2023). "OGTT-based analyses indicate that insulin secretion is impaired in TS and that this impairment contributes to hyperglycemia." (PMID 36875465, 2023). "Severe insulin deficiency triggers increases in counter-regulatory hormones such as cortisol, glucagon, and catecholamines, which results in hyperglycemia and ketoacidosis and requires treatment with exogenous insulin." (PMID 38165186, 2023). "DM is characterized by chronic hyperglycemia that results from disturbed insulin secretion or insulin dysfunction, or both." (PMID 37623897, 2023). "The hyperpolarized cell cannot open voltage-gated calcium channels; thus, the intracellular calcium concentration will not increase, preventing insulin granules’ exocytosis, resulting in decreased insulin secretion, hence hyperglycemia." (PMID 38108069, 2023). "A study of 188 extremely-low-birth-weight (ELBW) infants with a gestational age of 27.1 ± 2.2 weeks and a birth weight of 814.9 ± 151.9 g demonstrates a 32.9% incidence of hyperglycemia, with 22.8% rate of insulin treatment." (PMID 37371878, 2023). "The prevailing treatment of burn-induced hyperglycemia is insulin therapy, and it demonstrated favorable outcomes as it reduces muscle wasting and improves wound healing." (PMID 36779088, 2023). "As it is well known, T1DM is an autoimmune disease in which T lymphocytes destroy pancreatic beta cells, promoting beta cell islet damage, and consequently blocking insulin secretion, enhancing hyperglycemia." (PMID 37445852, 2023). "Bone marrow-derived stem cells reduced hyperglycemia in mice that have been made diabetic by streptozotocin.The stem cells induced proliferation of pancreatic β-cells and led to increased islet insulin content." (PMID 37761001, 2023). "The presence of hyperglycemia was considered as a result of the failure to maintain adequate pancreatic β-cell function to compensate for a decline in insulin sensitivity." (PMID 36769405, 2023). "More recently, in vitro and in vivo studies demonstrated that upregulation of miR-125b caused by AMPK repression in islet cells impairs glucose-stimulated insulin secretion and thus leads to hyperglycemia and glucose intolerance." (PMID 38139235, 2023). "In conclusion, NPH insulin treatment reduced hyperglycemia and improved cardiac function in diabetic rats." (PMID 37760247, 2023). "Ideally, a cross-over randomised clinical trial of activity vs. insulin for correction of hyperglycaemia would be required to make robust recommendations." (PMID 40303277, 2023).
Hyperglycemia (continued). "T2D is characterized by a persistent increase in blood sugar (hyperglycemia) as a result of the impaired action of insulin at the target tissue coupled with insufficient insulin secretion by the pancreatic β-cells." (PMID 38203409, 2023). "The receptor agonists of GLP-1 (GLP-1 RAs) are able to increase the hyperglycemia-induced insulin secretion and decrease glucagon secretion, delay gastric emptying, reduce appetite and caloric intake, and they are strongly recommended in T2DM treatment." (PMID 36675217, 2023). "The mechanism of stress-induced hyperglycemia after stroke appears to be due to consequences of increased hepatic gluconeogenesis and reduced sensitivity to insulin." (PMID 36777640, 2023). "Our results revealed that diabetic animals treated with WJMSC-CM for 60 days improved hyperglycemia and increased insulin secretion in treated diabetic rats." (PMID 37081849, 2023). "Impaired insulin production coincides with endoplasmic reticulum (ER) and oxidative stress contributing to hyperglycemia in T2DM." (PMID 38092892, 2023). "In contrast, Type 2 diabetes is characterized by hyperglycemia, insulin resistance, and also relative impairment in insulin secretion." (PMID 37264317, 2023). "This creates a vicious cycle that longer duration insulin treatment increases weight gain and IR which in turn increases insulin requirement for controlling hyperglycemia which in turn again leads to weight gain." (PMID 38111445, 2023). "This condition leads to an increase in insulin secretion by the pancreas, which in turn facilitates the presence of hyperglycemia in the organism due to the low absorption of insulin by the cells." (PMID 36900572, 2023). "The proper blood insulin concentrations and action of this hormone at the cellular level are needed to effectively reduce hyperglycemia." (PMID 38203600, 2023). "Plant-based foods, which are rich in dietary fiber and promote glycemic control, are also abundant in phytochemicals, such as polyphenols, that can reduce hyperglycemia, and enhance both acute insulin response and insulin sensitivity." (PMID 37432488, 2023). "The disease is characterized by a high blood glucose level (hyperglycemia) due to either the lowering of insulin production by the pancreas or the insulin resistance of target cells." (PMID 36899843, 2023). "Correspondingly, LCT dysregulated insulin dependent enzymes of glucose metabolism, resulting in hyperglycemia, decreased pyruvate, and increased lactate concentrations." (PMID 37463968, 2023). "In our initial analysis, we evaluated the animals at weaning and observed that the KI animals presented higher body weight and hyperglycemia, as well as low levels of insulin." (PMID 37189379, 2023). "Fucoidan is reported to prevent hyperglycemia and increase insulin production as a complex sulfated polysaccharide." (PMID 38068845, 2023). "It has been shown that chronic hyperglycemia gradually decreases insulin biosynthesis and secretion which is accompanied by reduced expression of very important insulin gene transcription factors MafA and PDX-1." (PMID 37720599, 2023). "During the DH arm some participants were administered glucagon right before dinner announcement, resulting in inadequate meal bolus insulin, and subsequent hyperglycemia." (PMID 36755913, 2023). "Xylazine use in animals can lead to hyperglycemia, induced in normoglycemic and insulin-dependent diabetic monkeys via reducing tissue sensitivity to insulin and glucose uptake." (PMID 37009344, 2023). "This combination of decreased insulin secretion and sensitivity induces and then aggravates hyperglycemia." (PMID 36895277, 2023). "Multiple evidences support that oxidative stress and hyperglycemia activate serine kinase cascades, which has several possible targets in the insulin signaling pathway, including insulin receptor substrate (IRS) proteins family." (PMID 37089941, 2023).
Hyperglycemia (continued). "Intravenous fluids and insulin infusion improved the patient's pancreatitis and explosive hyperglycemia." (PMID 37841238, 2023). "Regarding hyperglycemia, 12% thought they cannot give rapid-acting insulin to correct it unless it was given at mealtime, and 18% thought that long-acting insulin should be given to correct hyperglycemia." (PMID 37046268, 2023). "Fasting before surgery, which can be prolonged from 10 up to 16 h, can induce hyperglycemia due to a limitation of insulin action by the effect of counter-regulatory hormone action." (PMID 36904293, 2023). "The degradation of the nano-network with insulin release was glucose-mediated (facilitated in hyperglycaemia and inhibited in normal glucose levels) in both in vitro and in vivo studies." (PMID 37685946, 2023). "Subsequent fetal hyperglycaemia leads to fetal pancreatic beta cell hyperplasia, hypertrophy and insulin secretion, increasing glucose uptake and stimulating hepatic triglyceride and glycogen synthesis." (PMID 38288471, 2023). "Chronic hyperglycemia uses up insulin secretory granules in beta cells, reducing the quantity of insulin available for secretion, resulting in glucotoxicity." (PMID 36819346, 2023). "Oral glucose tolerance tests (OGTTs) in Laron syndrome showed slightly higher insulin secretion from the fasting level than the control (normal) group, but defective insulin secretion after glucose load leads to hyperglycemia when compared to controls." (PMID 37441495, 2023). "Participants are all aware that inadequate insulin dosage, voluntarily or involuntarily, results in hyperglycemia." (PMID 36754894, 2023). "Early observations conducted in a subgroup of asymptomatic participants in the DPT-1 trial, exhibiting fasting hyperglycaemia and 2 h glucose values >11.1 mmol/l, demonstrated reduced insulin sensitivity." (PMID 37712956, 2023). "Hyperglycemia reduced the expression of IRs; downregulated mediators of the insulin signaling pathway, including p-PI3K, p-GSK-3α/β, and p-Akt, in the cerebral cortex; and contributed to the loss of cognitive function." (PMID 37443762, 2023). "Prolonged hyperglycemia can increase insulin synthesis and islet amyloid peptides within B-cells, accumulating improper and misfolded proteins." (PMID 38161953, 2023). "In our case, both sisters developed hyperglycemia, which resulted in ketoacidosis and necessitated the use of subcutaneous insulin therapy." (PMID 37091967, 2023). "The disease is attributed to a multifactorial metabolic disorder characterized by either decreased insulin secretion and/or its action or reduced uptake by the target cells, leading to hyperglycemia." (PMID 37888717, 2023). "Type 2 diabetes (T2D) is a metabolic disease where peripheral tissues, such as muscle and liver, have developed resistance to insulin signaling, reducing the ability of the tissues to take up glucose, eventually leading to hyperglycemia." (PMID 37761001, 2023). "These conditions collectively disrupt beta-cell function and insulin release, contributing to hyperglycaemia and exacerbating oxidative stress." (PMID 37623239, 2023). "Raising the cellularity of the pancreatic islets of Langerhans and their apparent colonization by β-cells had an unanticipated impact in addition to lowering hyperglycemia and considerably increasing insulin levels." (PMID 36985818, 2023). "The combination of hyperglycemia and dyslipidemia (glucolipotoxicity) accelerates β-cell death, reducing insulin secretion, and further aggravating hyperglycemia." (PMID 38138997, 2023). "Together, this indicates that although mice fed HAMSB gained more weight compared to Ctr mice, they developed less severe hyperglycemia and have improved insulin sensitivity." (PMID 36901964, 2023). "Loss of epoxide hydroxylase, an enzyme that degrades EETs, significantly reduced hyperglycemia in streptozotocin-treated mice and increased glucose-dependent insulin secretion and reduced apoptosis in pancreatic β cells." (PMID 37298790, 2023).